ABCC6 (ATP binding cassette subfamily C member 6)
Diseases named in the same sentence as ABCC6 in open-access papers (continued):
Sharing a sentence is not in itself a finding about the gene and the disease.
cardiac hypertrophy (3 papers, 2013 to 2024). "Of note, Abcc6 deficiency mitigates cardiac hypertrophy that commonly characterizes elevated BP." (PMID 31704980, 2019). "Interestingly, only 24 month-old Abcc6−/− mice showed cardiac hypertrophy: the HW/BW ratios were 6.6±0.7 mg/g in Abcc6−/− mice group vs. 5.2±0.3 mg/g in WT mice group (p<0.01); and WGA staining revealed a clear increase in the size of cardiomyocytes." (PMID 23935882, 2013). "In order to clarify whether the cardiac hypertrophy observed in Abcc6−/− mice group was related to higher blood pressure, systolic blood pressure was measured by the tail-cuff plethysmography method (BP2000 Series II apparatus, Bioseb, France) in a subset of trained conscious mice." (PMID 23935882, 2013). "However, the development of cardiac hypertrophy in the 24-month-old Abcc6−/− mice suggests that old PXE patients might be prone to developing late cardiopathy." (PMID 23935882, 2013). "However, the development of cardiac hypertrophy in the 24-month-old Abcc6−/− mice does suggest that the old PXE patients could develop late cardiopathy." (PMID 23935882, 2013). "While none of the functional and histological parameters diverged significantly between the Abcc6−/− and WT mice groups at age of 6 and 12 months, the 24-month-old Abcc6−/− mice developed cardiac hypertrophy without contractile dysfunction." (PMID 23935882, 2013). "With the exception of a mild heart hypertrophy in the oldest pre-senescent animals, no major abnormalities could be evidenced in Abcc6−/− mice." (PMID 31704980, 2019).
chronic kidney disease (3 papers, 2015 to 2025). Impairment of the renal function secondary to chronic kidney damage persisting for three or more months. "Indeed, common traits such as chronic kidney disease or cardiovascular disorders have been linked to the ABCC6 gene." (PMID 26356190, 2015).
cystic fibrosis (3 papers, 2011 to 2023). Autosomal recessive disorder caused by pathogenic variants in the CFTR gene (cystic fibrosis transmembrane conductance regulator), which encodes a chloride and bicarbonate channel expressed in epithelial cells, and follow the diagnosis criteria. "Mutations of ABCC6 and CFTR are associated with their decreased functional expression that lead to a rare disease, pseudoxanthoma elasticum and the most frequent severe, monogenic inherited disease, cystic fibrosis, respectively." (PMID 28365738, 2017).
fibrosis (3 papers, 2019 to 2023). the formation of excess fibrous connective tissue in an organ or tissue in a reparative or reactive process. "To gain insights into the potential mechanism of ABCC6 regulating cardiac fibrosis, we performed RNA sequencing (RNA-seq) using total RNAs extracted from abcc6aΔ1/Δ1 mutant hearts and WT sibling hearts at eight months of age." (PMID 33383974, 2020).
hypophosphatemic rickets (3 papers, 2021 to 2022). Rickets due to low serum phosphate concentrations, the cause of which can be nutritional or genetic. "A very recent study showed that a small subset, 16.7%, of adult GACI patients with mutations in ABCC6 suffered from hypophosphatemic rickets, implying that bone is an affected tissue in relation to ABCC6 mutations." (PMID 35186933, 2022). "Specifically, some patients with ENPP1 variants develop hypophosphatemic rickets without a prior clinical history of GACI, while nearly all patients with ABCC6 variants present with PXE without a history of GACI." (PMID 35482848, 2022).
ischemic stroke (3 papers, 2022 to 2025). A stroke disorder caused by obstruction of blood flow to the brain, due to thrombotic (local blood clot formation) or embolic (due to a blood clot or other material traveling from another site) event. "This suggests that carriers of pathogenic ABCC6 variants have a significantly higher risk of developing ischemic stroke." (PMID 40725385, 2025). "Overall, this suggests a pro-ischemic state is present in the brain tissue of Abcc6-deficient mice, potentially explaining the higher risk of ischemic stroke in patients with pathogenic ABCC6 variants." (PMID 40725385, 2025). "The case–control study revealed that pathogenic ABCC6 variants were found in 16 out of 424 ischemic stroke patients (3.8%) compared to 2 out of 250 controls (0.8%), resulting in an odds ratio of 4.9 (p = 0.036)." (PMID 40725385, 2025). "Patients with ABCC6 mutations exhibit an increased risk of cerebrovascular events, including ischemic strokes." (PMID 40725385, 2025). "Interestingly, the authors found that heterozygous ABCC6 variants significantly increase the risk of ischemic stroke." (PMID 40725385, 2025). "That study highlighted the increased incidence of ischemic stroke in patients with PXE, including patients with monoallelic and biallelic pathogenic ABCC6 variants." (PMID 40725385, 2025).
kidney stones (3 papers, 2024 to 2026). "A common missense variant of ABCC6 (p.Arg1064Trp) has previously been associated with hemoglobin and other erythrocyte quantitative traits, as well as with calcium levels and kidney stones." (PMID 40758858, 2025). "We proposed that heterozygous ABCC6 mutations are an unrecognized risk factor for nephrolithiasis." (PMID 41908612, 2026). "The cg00089783 probe located intronic to ABCC6, is located near rs41278174, a missense variant (p.Arg1064Trp) associated with hemoglobin and other erythrocyte quantitative traits, as well as with calcium levels and kidney stones." (PMID 40758858, 2025). "Our data support kidney stones as a clinical outcome of ABCC6 disruption with partial gene deletions having lower penetrance than larger 16p13.11 deletions." (PMID 38185688, 2024). "By analyzing disease prevalence in subsets of CNV carriers, association signals could be fine-mapped to narrower regions, pinpointing candidate drivers—such as ABCC6 for kidney stones." (PMID 38185688, 2024).
Myocardial fibrosis (3 papers, 2013 to 2020). "However, dystrophic cardiac calcinosis (DCC) caused by Abcc6 mutations in murine inbred strains C3H/HeJ and DBA/2J developed a progressive myocardial fibrosis and calcification, suggesting that different murine genetic backgrounds give rise to distinct cardiac phenotypes." (PMID 33383974, 2020). "It is noteworthy that myocardial fibrosis and cardiomyocyte loss have not been reported as phenotypes associated with either human PXE or Abcc6 knockout mouse models." (PMID 33383974, 2020).
PXE-like syndrome (3 papers, 2013 to 2020). "These include generalized arterial calcification of infancy-1 and infancy-2 (GACI1 and GACI2), caused by bi-allelic mutations in ENPP1 or ABCC6, respectively, or the PXE-like syndrome with multiple coagulation factor deficiency, caused by bi-allelic GGCX mutations." (PMID 32372237, 2020).
acute lymphoblastic leukemia (2 papers, 2014 to 2023). Leukemia with an acute onset, characterized by the presence of lymphoblasts in the bone marrow and the peripheral blood. "In particular, the overexpression of MRP1 (ABCC1), MRP2 (ABCC2), MRP3 (ABCC3), MRP5 (ABCC5), and MRP6 (ABCC6) correlates with a poor prognosis in acute lymphoblastic leukemia in both adults and children." (PMID 36978873, 2023). "It has been reported that ABCC1, ABCC2, ABCC3, ABCC4, ABCC5 and ABCC6 play a significant role in MDR mediated non-small cell lung cancer (NSCLC), breast cancer, prostate cancer, colorectal cancer, ovarian cancer and acute lymphoblastic leukemia (ALL)." (PMID 25191874, 2014).
acute myeloid leukemia (2 papers, 2021 to 2024). Acute myeloid leukemia (AML) is a group of neoplasms arising from precursor cells committed to the myeloid cell-line differentiation. "Interestingly, MYTHO has been reported to be fused in frame with ABCC6 and ARL16 genes in acute myeloid leukemia and lung squamous cell carcinoma, but the pathogenetic role of the fused transcripts has not yet been explored." (PMID 38869949, 2024).
breast carcinoma (2 papers, 2022 to 2023). "However, further studies are required to elucidate whether RIMS3, LOC283710, and ABCC6 genes are medium-impact putative passengers involved in the molecular pathways of carcinogenesis, leading to gastric cancer, breast cancer, or GIST." (PMID 35912179, 2022). "Data obtained from the TCGA database also showed a statistically significant lowered average expression level of the ABCB1, ABCC4, ABCC6, and ABCG2 genes in patients with breast cancer compared to the control group." (PMID 36674773, 2023).
cardiac ischemia (2 papers, 2015 to 2021). "Furthermore, in a cardiac ischemia–reperfusion injury mice model could be demonstrated that the infarct size in heart tissue was increased in Abcc6−/− mice." (PMID 33483533, 2021).
cerebral small vessel disease (2 papers, 2025 to 2026). Cerebral small vessel disease is the term currently used to pathological processes that affect the brain parenchymal circulation (arterioles, capillaries, and veins). "This review investigates the connection between ABCC6 mutations and cerebral small vessel disease (SVD), expanding the understanding of PXE and related phenotypes." (PMID 40725385, 2025). "In recent years, the association of some pathogenic mutations of ABCC6 with a microvascular cerebral lesion pattern, or with a neuroimaging pattern consistent with a cerebral Small Vessel Disease (SVD), has been reported, albeit occasionally." (PMID 40725385, 2025). "This study aims to characterize the prevalence and clinical and neuroradiological phenotypes associated with monoallelic and biallelic ABCC6 variants in pediatric and adult patients presenting with arterial ischemic stroke or cerebral small vessel disease (CSVD)." (PMID 41751611, 2026).
colon cancer (2 papers, 2016 to 2022). "In order to identify new biomarkers and to suggest new therapeutic approaches, for colorectal cancer, we studied the role of ABCC6 in colon cancer cell lines Caco2 and HT29." (PMID 35645325, 2022). "In the present study, we investigated the role of ABCC6 in colon cancer evaluating the effect of Quercetin and Probenecid, inhibitors of the ectonucleotidase NT5E and ABCC6, respectively, on migration rate of Caco2 and HT29 cell lines." (PMID 35645325, 2022). "In this study, we investigated the role of ABCC6 in two colon cancer cell lines, which exhibit different ABCC6 expressions." (PMID 35645325, 2022). "Moreover, ABCC6 expression was found to be higher in human colon cancer-derived cell line Caco2, compared to normal intestine." (PMID 35645325, 2022). "The aim of the present study was to investigate the role of ABCC6 in the modulation of both the extracellular purinergic system and phosphatidylinositol 3-kinase (PI3K)/Akt pathway in colon cancer-derived Caco2 and HT29 cells." (PMID 35645325, 2022). "Therefore, in some colon cancers in which ABCC6 is overexpressed, it may have a primary role in controlling the extracellular purinergic system by feeding it with ATP, thus representing a potential target for a therapy aimed at mitigating invasiveness of those type of cancers." (PMID 35645325, 2022). "Notably, we observed that PXR controls the expression of genes that were previously reported to confer CSC chemoresistance or to have a negative impact on disease-free survival in colon cancer patients, including ABCG2, ABCC6, ALDH1A1, CYP3A4, or S100A10." (PMID 27448961, 2016).
glioma (2 papers, 2013 to 2020). A benign or malignant brain and spinal cord tumor that arises from glial cells (astrocytes, oligodendrocytes, ependymal cells). "Jeon reported that ID4 drive drug resistance of glioma cells by miR-9-SOX2-ABCC3/ABCC6 regulatory pathway." (PMID 32328189, 2020). "A novel regulatory pathway Inhibitor of differentiation 4 (ID4)-miR-9*-SOX2-ABCC3/ABCC6 was proposed, which induces the stemness potential of glioma stem cells and chemoresistance." (PMID 24358977, 2013).
hemorrhagic stroke (2 papers, 2022 to 2025). A stroke caused by a bleed on the brain. "For instance, Pathogenic or Likely Pathogenic variants in G6PD predispose to kernicterus associated with neonatal jaundice, while COL4A2 and ABCC6 are associated with both ischemic and hemorrhagic stroke." (PMID 41282771, 2025).
hypophosphatemia (2 papers, 2021 to 2023). Lower than normal levels of phosphates in the circulating blood. "It has been reported that the connection between ABCC6 mutations and hypophosphatemia is not very specific." (PMID 38248755, 2023).
myocardial infarction (2 papers, 2019 to 2023). Gross necrosis of the myocardium, as a result of interruption of the blood supply to the area, as in coronary thrombosis. "Further investigation is required to explain why some patients with ABCC6 mutations experience the severe GACI phenotype, which can lead to myocardial infarction and death in early infancy, while others experience a relatively mild phenotype of PXE." (PMID 38248755, 2023).
non-small cell lung carcinoma (2 papers, 2012 to 2014). A group of at least three distinct histological types of lung cancer, including non-small cell squamous cell carcinoma, adenocarcinoma, and large cell carcinoma. "It was recently shown that ABCC6 was five-fold up-regulated in gemcitabine resistant A549 non-small cell lung cancer cells suggesting that it also may be a factor in influencing gemcitabine resistance." (PMID 23028896, 2012).
ovarian carcinoma (2 papers, 2010 to 2024). A malignant neoplasm originating from the surface ovarian epithelium. "Our work found that kaempferol works synergistically with cisplatin in inhibiting ovarian cancer cell viability, and their inhibition on cell viabilities was induced through inhibiting ABCC6 and cMyc gene transcription." (PMID 20459793, 2010).
prostate carcinoma (2 papers, 2017 to 2022). A carcinoma that arises from epithelial cells of the prostate gland. "GSTM1, GSTM3 and ABCC6 were metabolism related genes whose abnormal regulation may contribute to prostate cancer progression." (PMID 29190897, 2017). "For example, eight ABC transporter genes (e.g., ABCA8, ABCC6, and ABCC9) were significantly downregulated in prostate cancer tissues compared with noncancerous tissues." (PMID 35280774, 2022).
retinal disease (2 papers, 2025). "In addition, R-loops were identified in 20 genes involved in retinal disease including Ush2a, Pcdh15, and Abcc6." (PMID 39345562, 2025).
retinitis pigmentosa (2 papers, 2023 to 2025). Retinitis pigmentosa (RP) is an inherited retinal dystrophy leading to progressive loss of the photoreceptors and retinal pigment epithelium and resulting in blindness usually after several decades. "Oxidative stress caused downregulation of Pdss1 and Abcc6, known to be involved in retinitis pigmentosa and retinopathy." (PMID 41326361, 2025).
sickle cell disease (2 papers, 2013 to 2017). Sickle cell anemias are chronic hemolytic diseases that may induce three types of acute accidents: severe anemia, severe bacterial infections, and ischemic vasoocclusive accidents (VOA) caused by sickle-shaped red blood cells obstructing small blood vessels and capillaries. "Skin manifestations resembling those seen in PXE and (in some cases) angioid streaks have been observed in individuals with β-thalassemia and sickle cell disease who clearly lack ABCC6 gene mutations." (PMID 28486967, 2017).
acquired metabolic disease (1 paper, 2017). An instance of metabolic disease that is acquired during the lifetime of the individual. "Data and a hypothesis on the possible roles of ABCC6 in acquired metabolic diseases are also discussed." (PMID 28891970, 2017).
amyloidosis (1 paper, 2015). A disorder characterized by the localized or diffuse accumulation of amyloid protein in various anatomic sites. "As this patient developed severe amyloidosis despite appropriate colchicine treatment, the possibility that ABCC6 deficiency contributed to the severity of FMF was raised." (PMID 26356190, 2015). "Though thus far no validation studies have been performed, the identification of ABCC6 variants would be important in improving the accuracy of amyloidosis risk prediction in patients and in extending our understanding of the pathophysiology of FMF." (PMID 26356190, 2015).
ankylosis (1 paper, 2022). Fixation and immobility of a joint. "Extracellular ATP release occurs through a variety of mechanisms, including tumor necrosis and apoptosis, vesicular exocytosis, active efflux via ATP-binding cassette subfamily C member 6 (ABCC6) and the ankylosis gene product ANK and diffusion via P2RX7 and Pannexin1 channels." (PMID 35515134, 2022).
Anxiety (1 paper, 2022). Intense feelings of nervousness, tension, or panic often arise in response to interpersonal stresses. "In the infant ABCC6 Deficiency cohort, 3/6 respondents reported a negative impact on peer-to-peer and family relationships; mental health due to fear of the unknown (3/6); and stress/anxiety (4/6)." (PMID 35895733, 2022).
calcinosis (1 paper, 2024). Deposition of calcium in the tissues. "Furthermore, KO models of ABCC6 demonstrated phenotypes associated with calcinosis, calcified skin, and calcified artery, suggesting an intrinsic role in metastatic calcification." (PMID 39526184, 2024).
clear cell renal cell carcinoma (1 paper, 2022). "In the clear cell renal cell carcinoma cohort, the DST, MED13 and ABCC6 gene mutation frequencies significantly differed among different low and high IP-score groups." (PMID 36700205, 2022).
colorectal cancer (1 paper, 2022). A primary or metastatic malignant neoplasm that affects the colon or rectum. "There is little information on the diagnostic or prognostic role of ABCC6 in some types of cancer, as well as, to the best of our knowledge, on the role of ABCC6 in colorectal cancer." (PMID 35645325, 2022).
disc degeneration (1 paper, 2022). "Overall, these results show that ABCC6 loss results in changes in collagen configuration that may reflect mild disc degeneration." (PMID 35186933, 2022). "When assessing the relationship between the disc compartment and vertebrae, Abcc6−/− mice had increased vertebral length and alterations in disc height and disc height index (DHI), parameters correlated with disc degeneration." (PMID 35186933, 2022).
hearing loss (1 paper, 2023). "It is worth noting that so far, there have not been any reports of hearing loss in patients with ABCC6 mutations that lead to GACI." (PMID 38248755, 2023).
hyperlipidemia (1 paper, 2012). "DCC is an acquired phenotype resulting from cardiovascular insults (ischemic injury or hyperlipidemia) and secondary to ABCC6 insufficiency." (PMID 23248644, 2012).
intervertebral disc degeneration (1 paper, 2022). "While dystrophic calcification is one of the known phenotypes of intervertebral disc degeneration, it is unknown whether PXE affects mineralization pathways in the disc and although ABCC6 is not expressed in the spine, its systemic effects on the spine have not been studied in detail." (PMID 35186933, 2022). "In Abcc6−/− mice we found no increase in calcification of the disc, but unexpectedly, these animals had reduced vertebral bone quality and could become a valuable model for gaining further insight into intervertebral disc degeneration." (PMID 35186933, 2022).
kidney injuries (1 paper, 2023). "Interestingly, Abcc6 deficiency led to protection against both acute and chronic rhabdomyolysis-induced kidney injuries." (PMID 38057332, 2023).
Liver cirrhosis (1 paper, 2022). "Liver cirrhosis with liver failure of any grade is associated with a deficit in plasma PPi, which is the result of a significant reduction in the gene expression levels of key regulators of PPi synthesis in the liver, i.e., ABCC6 and ENPP1, concomitant to enhanced degradation via TNAP." (PMID 35884801, 2022).
liver diseases (1 paper, 2018). "However, we cannot exclude that the contribution of the ABCC6 in the regulation of the purinergic system can become more important in some liver diseases." (PMID 30155470, 2018).